DNM2 (dynamin 2)
Diseases named in the same sentence as DNM2 in open-access papers (continued):
Sharing a sentence is not in itself a finding about the gene and the disease.
centronuclear myopathy (continued). "In this regard, it is notable that pathogenic variants in DNM2 are well known to cause peripheral neuropathy, as well as centronuclear myopathy (CNM), characterized by weakness and slow progressive muscle loss." (PMID 33810506, 2021). "Dominant dynamin 2 (DNM2) mutations lead to either mild adult onset or severe autosomal dominant centronuclear myopathy (ADCNM)." (PMID 32809972, 2020). "Among these, mutations in myotubularin (MTM1), amphiphysin 2 (BIN1), and dynamin 2 (DNM2) lead to different forms of centronuclear myopathy (CNM)." (PMID 31680794, 2019). "The majority of CMT-associated DNM2 mutations is located in the N-terminal part of the pleckstrin homology domain, while a distinct set of mutations, mainly those found in the middle, PH, and PH/GTPase-effector boundary, is linked to autosomal-dominant centronuclear myopathy." (PMID 26517984, 2015). "In addition to the BIN1-related form, heterozygous missense variants in hJUMPY, a novel phosphoinositide phosphatase with functional similarities to myotubularin, were recently identified in two sporadic cases with features of centronuclear myopathy and an additional DNM2 mutation in one case." (PMID 18817572, 2008). "One of the therapeutic strategies is the rAAV-shDnm2, which lowers DNM2 production, rescuing myofiber architecture in Dnm2-knockout models of centronuclear myopathy." (PMID 40869293, 2025). "Based on these findings, a phase I/II, dose escalation trial testing the molecule DYN101 (an ASO directed against human DNM2 RNA), was performed on patients affected by XLMTM and DNM2 centronuclear myopathies." (PMID 38678519, 2024). "Thus, our study supports the recent finding that a defect of autophagy probably plays a role in the pathophysiology of diseases caused by mutations in DNM2 and suggest that those could include microcytic anemia and Charcot-Marie-Tooth diseases, in addition to centronuclear myopathy." (PMID 37060997, 2023). "One patient (Pt 15) with centronuclear myopathy due to DNM2 heterozygous variation presented with predominant weakness of the distal lower limbs." (PMID 35081925, 2022). "Reduction of DNM2 by systemic delivery of ASOs was shown to rescue myotubular myopathy in 3-week-old Mtm1−/y mice in a dose–response manner." (PMID 35642830, 2022). "In vivo, overexpressing the ubiquitous dynamin 2 isoform correlates with severe forms of centronuclear myopathy, while overexpressing the muscle-specific isoform leads to hallmarks seen in milder cases of the disease." (PMID 36369230, 2022). "Here, we studied the role of the different DNM2 isoforms in healthy skeletal muscle, in centronuclear myopathy, and the therapeutic mechanism of DNM2 targeting in CNM." (PMID 36369230, 2022). "DNM2 is a target of miR-133a-1 and miR-133a-2 and silencing of miR-133a in mouse induces an increase in DNM2 in skeletal muscle and a centronuclear myopathy phenotype." (PMID 34294140, 2021). "Patients and mouse model of myotubular myopathy exhibit an increased DNM2 expression and a forced DNM2 reduction restores phenotypes and lifespan in a mouse model of the disease." (PMID 34294140, 2021). "Since early descriptions, it was evident that DNM2-related centronuclear myopathy can present with mild childhood, adolescent and late-onset forms, but also with severe forms of congenital myopathy." (PMID 32456280, 2020). "Mtm1-KO causes an overexpression of DNM2 and systemic administration of an ASO downregulating Dnm2 mRNA prevented and reverted myotubular myopathy in Mtm1-KO mice." (PMID 33324928, 2020). "Studies conducted on centronuclear myopathy knock-in mice also confirmed that DNM2 reduction rescued DNM2-related centronuclear myopathy." (PMID 33339321, 2020). "Currently, DYN101, an AO therapeutic designed by Dynacure to modulate the expression of DNM2 entered an early-phase trial clinical trial (NCT04033159) on centronuclear myopathy patients." (PMID 33339321, 2020).
centronuclear myopathy (continued). "Myotubular myopathy) is caused by LoF mutations in the MTM1 gene, while autosomal dominant CNM (AD-CNM) is mostly caused by GoF mutations in the DNM2 gene." (PMID 33324928, 2020). "The role of dynamin-2 (DNM2) in pathology of autosomal dominant centronuclear myopathy is investigated and reported by several researchers." (PMID 31037085, 2019). "Restoring either muscle force in a CNM mouse model or DNM2 function in patient‐derived cells is an essential breakthrough towards future gene‐based therapy for dominant centronuclear myopathy." (PMID 29246969, 2018). "There are considerable pathomechanistic overlaps between centronuclear myopathies, particularly in relation to triad defects and alterations in DNM2 protein levels." (PMID 30451841, 2018). "The DNM2 gene was previously found to be mutated in Charcot-Marie-Tooth neuropathy-type CMT2M and centronuclear myopathy (CNM)." (PMID 29670510, 2018). "Altogether, these results suggest that intramuscular injections of ASOs reduce DNM2 levels and prevent myotubular myopathy in Mtm1KO mice." (PMID 28589938, 2017). "Jumpy/MTMR14 PI3-phosphatase and Dynamin-2 (DNM2) GTPase, two causative genes of human centronuclear myopathy, are required for not only T-tubule maintenance but also proper progression of autophagy." (PMID 28063257, 2017). "Genetic deletion of miR-133a-1 and miR-133a-2 in muscle leads to an adult-onset centronuclear myopathy, which correlates with the dysregulation of dynamin 2 (DNM2)." (PMID 25078649, 2014). "Specific missense mutations and short deletions into the structural domains of dynamin-2 have been associated with two congenital autosomic neuromuscular disorders: Charcot–Marie–Tooth neuropathy (CMT) and centronuclear myopathy (CNM)." (PMID 24065954, 2013). "Centronuclear and myotubular myopathies (CNMs) are rare, inherited muscle disorders characterized by muscle atrophy, weakness, and altered muscle fiber structure, primarily caused by mutations in MTM1, DNM2, or BIN1." (PMID 41373724, 2025). "Indeed, DNM2 protein level is increased in skeletal muscle of the Mtm1−/y mouse, an induced increase of DNM2 in WT mice created a myotubular myopathy phenotypes, and normalization of DNM2 level fully rescued the Mtm1−/y mouse." (PMID 39625536, 2024). "Furthermore, in a mouse model of autosomal dominant centronuclear myopathy (AD-CNM), treatment with allele-specific siRNAs at advanced stages of the disease reduced around 40% of the mutant DNM2 allele expression and partially rescued the muscle force impairment and morphologic abnormalities." (PMID 35409410, 2022). "Previous mouse studies suggested that reduction of the total dynamin 2 pool could be therapeutic for centronuclear myopathies." (PMID 36369230, 2022). "X-linked CNM (XLCNM, also called myotubular myopathy) is caused by mutations in the phosphoinositide phosphatase myotubularin (MTM1; MIM#310400) and autosomal dominant and recessive CNM due to mutations in the DNM2 partner amphiphysin 2 (BIN1; MIM#255200)." (PMID 36369230, 2022). "In cell-based assays, we show that a centronuclear myopathy-related mutation in the ubiquitous but not the muscle-specific dynamin 2 isoform causes increased membrane fission." (PMID 36369230, 2022). "DNM2 overexpression may have also indirect deleterious impacts through concomitant upregulation of miRNA located at the DNM2 locus as already demonstrated for the miR199a-1 in the pathophysiology of the myotubular myopathy." (PMID 34294140, 2021). "DNM2 was also previously found mutated in Charcot–Marie–Tooth neuropathy type CMT2M, a motor and sensory neuropathy primarily affecting peripheral nerves and in centronuclear myopathy (CNM), presenting with primary damage in skeletal muscles." (PMID 32138249, 2020).
centronuclear myopathy (continued). "DNM2-related centronuclear myopathy is histologically characterized by the presence of a substantial number of central nuclei, type 1 muscle fiber predominance and hypotrophy and the presence of sarcoplasmic strands in oxidative stains, radiating from the central nucleus to the periphery." (PMID 32456280, 2020). "Necklace fibres with nuclear internalisation have been reported as a histological hallmark of X-linked myotubular myopathy related to mutations in the phosphoinositide phosphatase myotubularin 1 (MTM1) gene and also a late-onset dynamin-2 (DNM2) gene-related centronuclear myopathy." (PMID 32444983, 2020). "Moreover, as ASO leading to DNM2 decrease was able to rescue myotubular myopathy, our findings support that a similar treatment can be applied to several myopathies." (PMID 32809972, 2020). "Similarly, the identification of DNM2 and BIN1 as genetic modulators of MTM1, all of which cause a centronuclear myopathy, indicates intimate crosstalk among genes involved in the same (or similar) disorders." (PMID 31413155, 2019). "All these studies performed in the KI-Dnm2R465W/+ mouse model led to better define the bases of the muscle phenotype in DNM2-related centronuclear myopathy and open a new field of investigation on the contribution of satellite cells in this congenital myopathy." (PMID 30733559, 2019). "DNM2 is a membrane fission protein well known for its role in regulating endocytic vesicle release, and has emerged as a crucial player in the pathogenesis of centronuclear myopathy." (PMID 30426359, 2018). "Indeed, Tasfaout and collaborators succeeded to revert the phenotype of MTM1‐myotubular myopathy mouse model by knock‐down Dnm2 using anti‐sense oligonucleotide." (PMID 29246969, 2018). "In vitro and murine models of DNM2-related centronuclear myopathy have begun to shed light on how DNM2 contributes to muscle defects; however, better models are needed to recapitulate disease characteristics and gain more meaningful insight into disease pathogenesis." (PMID 23418470, 2013). "Centronuclear myopathy (CNM), a severe congenital myopathy characterized by T-tubule defects and muscle weakness, is associated with mutations in three membrane trafficking-related genes: BIN1 (Bridging Integrator-1; also known as Amphiphysin 2, Amph2), DNM2 (Dynamin 2), and MTM1 (Myotubularin 1)." (PMID 41499502, 2026). "However, SH3 domains are typically promiscuous and it is expected that other, so far unknown partners of BIN1 exist besides DNM2, that also participate in the development of centronuclear myopathy." (PMID 38995680, 2024). "Mutations in the DNM2 gene are associated with three distinct autosomal dominant neuromuscular disorders: Charcot–Marie–Tooth neuropathy (CMT1B, MIM# 606482), spastic paraplegia and centronuclear myopathy (ADCNM, MIM# 160150), the predominant centronuclear myopathy (CNM) form in adult patients." (PMID 35244154, 2022). "Mutations in the gene encoding dynamin 2 (DNM2), a GTPase that catalyzes membrane constriction and fission, are associated with two autosomal-dominant motor disorders, Charcot-Marie-Tooth disease (CMT) and centronuclear myopathy (CNM), which affect nerve and muscle, respectively." (PMID 34744632, 2021). "Within the group of centronuclear myopathies, MTM1, DNM2 and BIN1 are interconnected due to the role they play in membrane trafficking." (PMID 38678519, 2024). "Preclinical studies showed that the downregulation of DNM2, whose levels are increased also in BIN1 and MTM1-related centronuclear myopathies, resulted in clinical and histological improvements." (PMID 38678519, 2024). "Its beneficial effect on muscle function was demonstrated in preclinical models of BIN1, DNM2 and MTM1 related centronuclear myopathies." (PMID 38678519, 2024).
centronuclear myopathy (continued). "Autosomal-dominant centronuclear myopathy (CNM), dominant Charcot-Marie-Tooth disease (CMT), and autosomal-dominant hereditary spastic paraplegia (HSP) are 3 distinct neuromuscular disorders associated with mutations in DNM2 gene." (PMID 31017801, 2019). "Here, we demonstrate that intramuscular injection and systemic delivery of Dnm2 ASOs efficiently reduced DNM2 protein levels and rescue different CNM features in the Mtm1KO murine model of myotubular myopathy." (PMID 28589938, 2017). "In this study we demonstrated that DNM2 knockdown, through ASO delivery, prevents myotubular myopathy in Mtm1KO mouse model by extending the lifespan and restoring muscle force, mass and histology in a dose-dependent manner." (PMID 28589938, 2017). "Conversely, systemic postnatal AAV delivery of human DNM2 increased DNM2 in muscle but failed to transduce nerves and paradoxically worsened the muscle pathology, producing centronuclear myopathy-like features." (PMID 41683892, 2026). "Our results highlight that the ubiquitous and not the muscle-specific dynamin 2 isoform is the main modifier contributing to centronuclear myopathy pathology." (PMID 36369230, 2022). "Thus, dysfunctional or dysregulated DNM2 connects hereditary spastic paraplegia, Charcot-Marie-Tooth neuropathy (CMT2M), and centronuclear myopathy (CNM), and according to our new findings, it also connects at least a subset of sporadic ALS cases." (PMID 29670510, 2018). "Previous work from our laboratory revealed that in the soleus and gluteus minimus muscles of mice overexpressing PLN (PlnOE), SERCA function was impaired, dynamin 2 (3–5 fold) and SLN (7–9 fold) were upregulated, and features of human centronuclear myopathy (CNM) were observed." (PMID 27134770, 2016). "To identify BIN1 mutations affecting its function in skeletal muscle, we sequenced the muscle-specific exon 11 and the adjacent splice-relevant intronic regions in a cohort of 84 patients with various forms of centronuclear myopathy and without mutations in MTM1, DNM2, or in the other BIN1 exons." (PMID 23754947, 2013). "However, we speculate that the mechanism responsible for these observed multinucleated fibers is not the same as in centronuclear myopathies caused by mutations in BIN1, MTM1, or DNM2, as classically those result in the persistence of myofibers with a single, well-centralized nucleus." (PMID 39264856, 2024).
breast cancer (29 papers, 2012 to 2026). A primary or metastatic malignant neoplasm involving the breast. "Among these cases, cytoplasmic overexpression was correlated with a specific cancer sub-type (invasive ductal carcinoma) whereas membranous DNM2 staining was associated with vascular invasion, an indicator of aggressiveness of breast cancer." (PMID 34294140, 2021). "We showed that dynamin 2 protein expression has an association with more aggressive tumor behavior and more advanced disease in the patients with breast cancer; therefore, dynamin 2 molecule could be considered as an indicator of disease progression and aggressiveness." (PMID 33250680, 2020). "Our previous findings have also demonstrated that nuclear DNM2 overexpression has a considerable relationship with pT stage, grade, and aggressiveness in breast cancer and clear cell renal cell carcinoma." (PMID 39610009, 2024). "Our recent studies have also indicated the relationship between DNM2 overexpression and an aggressive phenotype of breast cancer and clear cell renal cell carcinoma." (PMID 39610009, 2024). "We also found the expression level of DNM2 increased in platelets from breast cancer patients, as did p-PKCα levels." (PMID 39113702, 2024). "DNM2 provides the proper delivery from late recycling endosomes of MT1-MMP to the invadopodia of breast cancer cells and is required for their ability to degrade matrix." (PMID 34294140, 2021). "It was demonstrated in breast cancer cells that DNM2-dependent endocytosis of the IGF1-receptor is required for the prolactin-induced increase of IGF1-receptor phosphorylation inducing IGF1-receptor signaling." (PMID 34294140, 2021). "Reduced expression of DNM2 significantly improved tumor response to cyclophosphamide, a drug widely used in chemotherapy of breast cancers, leading to reduced tumor volume." (PMID 34294140, 2021). "Both expression and localization of DNM2 were studied in tumor and adjacent normal tissue from 113 patients affected by several types of breast cancers." (PMID 34294140, 2021). "In melanoma and breast cancer cell lines, DNM2 inhibition impacts cell invasion by reducing extracellular matrix remodelling and the number of degrading cells." (PMID 34294140, 2021). "In this study, the expression levels of dynamin 2 were investigated for the first time in a collection of 113 breast cancer tissue samples and normal cases as well as the clinicopathological parameters." (PMID 33250680, 2020). "Additionally, in the platelet culture system treated with MDA-MB-231 cells, we added neutralizing antibodies against DNM2 and found that this significantly reduced the release of EVs from breast cancer platelets." (PMID 39113702, 2024). "In order to assess whether lowering DNM2 levels would increase sensitivity to chemotherapy, breast cancer cells expressing an inducible shRNA to silence DNM2 by RNA interference were implanted into mammary fat pads of mice." (PMID 34294140, 2021). "Numerous studies are now available demonstrating the interest of DNM2 as a biomarker for prognosis of tumor invasion and metastasis, as exemplified for cervical cancers, or to predict therapy efficacy as shown in a sub-group of breast cancer." (PMID 34294140, 2021). "In addition, the level of dynamin 2 membranous expression is associated with the increased tumor invasion, which results in more advanced disease and may be considered as an indicator of the extent of invasion of breast cancer cells into blood vessels, metastases, and progression." (PMID 33250680, 2020). "Overall, our results showed that, the increased expression of dynamin 2 in breast cancer tissue samples rather than normal cases and nuclear expression level of dynamin 2 molecule is associated with the tumor stages and histological grades of tumor cells." (PMID 33250680, 2020).
breast cancer (continued). "In addition, analysis of the cytoplasmic expression levels of this molecule revealed that, there was a statistically significant difference between the expression levels of dynamin 2 among the different breast cancer subtypes (P = 0.003)." (PMID 33250680, 2020). "Over-activation of such signal transduction pathways, requiring a DNM2-dependent receptor internalization for their downstream signaling, may be deleterious by increasing tumor cell proliferation and survival as suggested in breast cancer and leukemia cells." (PMID 34294140, 2021). "Activated PKCα was conjugated with Dynamin 2 (DNM2), enhanced the generation of DNM2, and facilitated the release of PEVs from platelets, while PEVs transferred miR-1297 from platelets to breast cancer cells to promote tumor progression." (PMID 39113702, 2024). "To demonstrate the interaction among TM4SF1, PKCα, and DNM2, we examined the levels of PKCα, p-PKCα, DNM2, and TM4SF1 proteins in platelets from breast cancer patients treated with a PKCα inhibitor or an anti-TM4SF1 neutralizing antibody." (PMID 39113702, 2024). "Mass spectrometry and coimmunoprecipitation assays showed that Dynamin 2 (DNM2), a member of the guanosine-triphosphate-binding protein family, might cooperate with activated PKCα to regulate PEV production by breast cancer platelets." (PMID 39113702, 2024).
Charcot-Marie-Tooth disease (14 papers, 2008 to 2026). "Charcot-Marie-Tooth disease (CMT) is a progressive disorder of the peripheral nervous system and a genetic variant of CMT is caused by mutations in dynamin-2 (DNM2)." (PMID 25165726, 2014). "Charcot-Marie-Tooth disease (CMT), caused by dominant loss-of-function mutations in DNM2, encoding the GTPase dynamin-2, impairs motor and sensory function." (PMID 41683892, 2026). "Interestingly, the degradation of apoptotic cells utilizes many genes that also function in receptor-mediated endocytosis, and their mutation can result in various human diseases (e.g., mammalian orthologues of RAB-5 in tuberous sclerosis, Dynamin-2 and Rab7 in Charcot-Marie-Tooth disease)." (PMID 21494661, 2011).